RAG1 (recombination activating 1)
Diseases named in the same sentence as RAG1 in open-access papers (continued):
Sharing a sentence is not in itself a finding about the gene and the disease.
eosinophilia (10 papers, 2016 to 2025). "In contrast to the Th2-dependent asthma models, the models using papain extract or Alternaria-induced asthma still elicit eosinophilia in Rag1-deficient mice." (PMID 40276331, 2025). "Hp‐TGM was also effective in abrogating A. alternata‐induced eosinophilia in RAG‐1‐deficient mice, confirming that innate responses were suppressed directly without involvement of adaptive lymphocytes." (PMID 35758054, 2022). "However, in Rag1-deficient mice which lack T and B cells or Th2-deficient mice, eosinophilia is only abrogated in some asthma models." (PMID 40276331, 2025). "However, despite a reduction in airway eosinophilia, histopathological analysis showed that T. muris-infected Rag1−/− mice were equally susceptible to mucus overproduction in the large airways." (PMID 26644379, 2016). "Since we observed a consistent upregulation of IL-10 in the lungs of T. muris-infected C57BL/6 and Rag1−/− mice, we hypothesized that blocking IL-10 activity would restore susceptibility to eosinophilia in infected Rag1−/− mice after papain challenge." (PMID 26644379, 2016). "Infected Rag1-/- mice treated with anti-CD90.2 antibodies display jejunal eosinophilia (SiglecF+ immune cells) in the lamina propria." (PMID 39083533, 2024). "Anti-IL-5 treated papain challenged Rag1−/− and WT mice were unable to induce eosinophilia in the bone marrow and BAL." (PMID 32582171, 2020). "In contrast, while IL-33 increased lung eosinophils in Rag1–/– mice, animals treated with IL-33 and IL-2c had a significant reduction in lung eosinophilia." (PMID 29196657, 2017). "More precisely, in Rag1-deficient mice eosinophilia is absent in models of HDM-induced asthma, allergic bronchopulmonary aspergillosis or OVA-induced asthma." (PMID 40276331, 2025). "Accordingly, we speculate that the immunosuppressive effects of IL-10 on cells that produce eosinophilic chemoattractants result in mitigated eosinophil recruitment under normal conditions, an effect that was lost in Rag1−/− mice resulting in exaggerated eosinophilia." (PMID 34326406, 2021). "We also explored the possibility whether the eosinophilia and activation of ILC2 cells could be inhibited by 2′3′-cGAMP codelivered or delivered afterward with A. flavus in Rag1–/– mice or WT mice." (PMID 33400692, 2021). "Thus, in the current study we sought to assess the role of ILC2s in the regulation of allergen- and IL-33-induced bone marrow eosinophilia utilizing wild type (WT) mice, Rag1−/− mice lacking mature T and B cells but retain ILCs, and mice lacking all lymphocytes (Rag2−/−Il2rg−/−)." (PMID 32582171, 2020).
autoimmune disease (9 papers, 2011 to 2024). A disorder resulting from loss of function or tissue destruction of an organ or multiple organs, arising from humoral or cellular immune responses of the individual to their own tissue constituents. "The generated Rag1 mutant rat on a defined genetic background can provide a useful tool for studies of the immune system, in transplantation studies, and in autoimmune diseases." (PMID 23136839, 2012). "Lastly, TCF-1-/- mice and Rag1-/- mice adoptively transferred with TCF-1-/- T cells were more susceptible to induction of EAE, a Th17-dependent autoimmune disease." (PMID 21935461, 2011). "Our approach was successfully applied on the IgH repertoires of patients suffering from monogenic hypomorphic RAG1 and 2 deficiency (pRD) or polygenic systemic lupus erythematosus (SLE) autoimmune diseases to identify relatives of AR IgH sequences and to track their fate in AIRRs." (PMID 36613668, 2022). "In addition to uncovering lower-frequency autoantigens, antigen overlap between APS1 and other syndromic autoimmune diseases, including IPEX and RAG1/2 deficiency, were evaluated." (PMID 36300623, 2022).
colon cancer (9 papers, 2012 to 2026). "However, in T- and B-cell-null Rag1-deficient (Rag1-/-) mice, colon cancer growth was mildly inhibited following Tri-NAb treatment, but this effect was not as pronounced as that observed in immunocompetent C57BL/6 mice." (PMID 39043643, 2024). "As anticipated, ATXN3 ablation led to a pronounced increase in HCT116 xenograft colon cancer growth in RAG1 mutant mice." (PMID 38815863, 2024). "Human colon cancer HCT116 cells transfected with VASH1-specific or control shRNA were injected tail intravenously into Rag1−/− mice." (PMID 25797264, 2015). "To further demonstrate the malignancy of colon tumors developed in Hltf -/-/Apcmin/+ mice, we derived cells from these tumors and then subcutaneously injected them into Rag1-/-/IL2-/- immunodeficient mice." (PMID 22452792, 2012). "HCT116 human colon cancer cells grew progressively in Rag1‐/‐ mice." (PMID 34747157, 2022). "Human colon cancer HCT116 cells transfected with VASH1 shRNA or control shRNA, were subcutaneously injected into Rag1−/− mice." (PMID 25797264, 2015). "In addition, they found that the human colon cancer cells (SW480) expressed SNC73, Ig heavy chain α1, recombination activating gene 1 (RAG1), and RAG2." (PMID 34226529, 2021).
atherosclerosis (8 papers, 2013 to 2023). A disease characterized by the build-up of fatty material and calcium deposition in the arterial wall resulting in partial or complete occlusion of the arterial lumen. "BALB/c mice homozygous for targeted immunological mutations like Rag1-knockout, Rag2-knockout and the Il2rg-knockout are suitable recipients for human hematopoetic stem cells and therefore the study of atherosclerosis in humanized mice." (PMID 27564380, 2016). "To test if T‐cell specific deficiency of DPP4 may reduce atherosclerosis, we adoptively transferred Dpp4+/+ or Dpp4−/− pan T cells into lymphocyte deficient Rag1−/− mice in order to generate T‐cell specific DPP4 deficient chimeric mice." (PMID 36683148, 2023). "Mice models lacking lymphocytes (athymic nu/nu mice—deficient in B and T cells and ILCs), or Rag1–/– mice (deficient in B and T cells) or the use of T cell depletion models were shown either to be protected from atherosclerosis or to develop more atherosclerosis." (PMID 35966516, 2022). "The role of B1b cells in atherosclerosis is not fully understood; however, adoptive transfer of B1b cells to Rag1−/−/ApoE−/− mice reduces atherosclerosis." (PMID 31653058, 2019).
breast cancer (7 papers, 2014 to 2024). A primary or metastatic malignant neoplasm involving the breast. "To investigate the role of adaptive immune cells in TSLP-induced breast cancer suppression, we transferred naive CD4+ or CD8+ T cells from WT mice into MMTV-PyMTtg, Rag1−/− (PyMttg Rag1KO) animals with or without K14-Tslp transgene." (PMID 35657353, 2022).
influenza (7 papers, 2011 to 2024). An acute viral infection of the respiratory tract, occurring in isolated cases, in epidemics, or in pandemics; it is caused by serologically different strains of viruses (influenzaviruses) designated A, B, and C, has a 3-day incubation period, and usually lasts for 3 to 10 days. "Among proteins related to multiple infections, 30 out of 38 were associated with influenza, including total APOE, APOE3, APOE4 (apolipoproteins), DEFB4A (an antimicrobial peptide) and RAG1 (a VDJ recombination activator)." (PMID 39143319, 2024). "To first assess the potential of 4’-FlU to pharmacologically manage influenza in high-risk hosts, we infected interferon α/β receptor knockout (IFNAR1 KO) and V(D)J recombination activation gene RAG-1 KO mice with pdmCa09." (PMID 37068076, 2023). "Of note, RAG1−/− mice reconstituted with IFN-γ−/− adaptive immune cells demonstrated increased lung injury following influenza infection." (PMID 25500584, 2014). "Therefore, as an alternative approach, we demonstrated that adoptive transfer of CD8+ T cells isolated from naïve SOCS1−/−IFN-γ−/− mice rescued RAG1−/− animals from lethal influenza infection." (PMID 25500584, 2014). "Surprisingly, despite their markedly reduced viral burdens, RAG1−/− mice reconstituted with SOCS1−/−IFN-γ−/− adaptive immune cells failed to ameliorate influenza-induced lung injury." (PMID 25500584, 2014). "Similar to our recently reported findings in the murine influenza infection model, we noted minimal IL-10 secretion in RSV infected Rag1-/- mice and localized IL-10 production by effector T cells in the infected lungs using the IL-10 reporter Vert-X mice for infection." (PMID 21829368, 2011).
acute lymphoblastic leukemia (6 papers, 2017 to 2024). Leukemia with an acute onset, characterized by the presence of lymphoblasts in the bone marrow and the peripheral blood. "The underlying diseases were hemophagocytic lymphohistocytosis (HLH), (pre-B) acute lymphoblastic leukemia (preB-ALL), and hypomorphic RAG1 deficiency." (PMID 37958995, 2023). "Inhibition of activation of Artemis in acute lymphoblastic leukemia (ALL) cells would result in chromosomal breaks because the large majority of ALL tumors have ongoing expression of RAG1/2." (PMID 35801871, 2022). "Finally, the RAG1/RAG2 recombinase, which catalyzes the V(D)J recombination, is a driver of the genetic instability linked to lymphoblastic leukemia." (PMID 33407840, 2021). "Additionally, we showed that non-core RAG1 region deletion leads to increased Rag1c/c expression and high RAG expression related to low survival in pediatric acute lymphoid leukemia." (PMID 39056282, 2024).
anemia (6 papers, 2008 to 2024). A reduction in the number of red blood cells, the amount of hemoglobin, and/or the volume of packed red blood cells. "AIHA, caused by RAG1 gene mutations, typically presents as severe, recurrent, and refractory anemia." (PMID 39720732, 2024). "Indeed, adoptive transfer of Th2 cells also significantly reduced parasitemia, suggesting a functional loss of hemoglobin and severe anemia were also prevented in Rag1–/–mice given Th2 cells." (PMID 26147567, 2015). "While anemia responded to intravenous (IV) methylprednisolone pulses in 2 patients (RAG1 and NHEJ1 defect each), pt.42 with STK4 defect received IV rituximab (375 mg/m2 2 doses) for control of AIHA and she did not have further relapse of AIHA for next 1.5 years." (PMID 33628209, 2020). "We confirmed work from our lab and others showing that MT growth led to dysregulated hemopoiesis characterized by splenomegaly, granulocytic expansion, and anemia in both syngeneic MMTV and Rag1−/− hosts." (PMID 36911097, 2023).
Anxiety (6 papers, 2013 to 2024). Intense feelings of nervousness, tension, or panic often arise in response to interpersonal stresses. "It should be subject of future experiments to determine the connection of Rag1-deficiency/pharmacological immune modulation, microglial activation, and anxiety-like behavior." (PMID 38435059, 2024). "Lactobacillus rhamnosus, combined with L. helveticus, has been reported to alleviate anxiety- and depression-like behaviors in B- and T-cell-deficient Rag1−/− mice." (PMID 39130643, 2024). "We have previously shown that T and B cell-deficient recombinase activating gene (RAG-1)−∕− knockout mice have an increased level of anxiety-like behavior and altered gene expression involved in olfaction." (PMID 26441494, 2015). "Some studies indicate that Rag1-deficiency leads to increased anxiety- and depression-like behavior in mice, and indeed Rag1-deficiency increased anxiety-like behavior of wt mice in our study." (PMID 38435059, 2024). "Our recent characterization of the emotional behavior of immunodeficient recombination activation gene (RAG)-1 knockout mice has revealed an increased level of anxiety-like behavior in these animals." (PMID 26441494, 2015). "When we compared the number of center entries (considered an anxiety-like behavior parameter) in the three lines, we observed a significant reduction in RAG-1−/− mice compared with WT mice." (PMID 23838891, 2013). "To further confirm these results, we sought to investigate if the repopulation of RAG-1−/− with T cells would rescue the increased anxiety observed in these mice." (PMID 23838891, 2013). "Regarding anxiety-related parameters, Rag1-deficiency did not lead to any behavioral changes of male Spg11−/− mice in the DLB." (PMID 38435059, 2024). "In contrast, the transfer of CD4+ T cells from naive mice to Rag1–/– mice did not affect anxiety behavior." (PMID 37156764, 2023). "Surprisingly, these anxiety-like behaviors were significantly reverted in RAG-1−/−/OT-II but not RAG-1−/−/OT-I transgenic mice." (PMID 23838891, 2013). "The depressive and anxiety-like behavior exhibited by Rag1–/– or Rag2–/– mice lacking T cells can be improved by transplantation of splenocytes/lymphocytes from chronically stressed mice, and immunization with myelin-related peptides can further reduce stress-induced anxiety." (PMID 37156764, 2023). "However, Rag1–/– mice (which have no T cells) have also shown to exhibit augmented instead of reduced anxiety-like behavior, which is rescuable by T cell transfer in distinct anxiety models." (PMID 33717157, 2021).
glioma (6 papers, 2010 to 2025). A benign or malignant brain and spinal cord tumor that arises from glial cells (astrocytes, oligodendrocytes, ependymal cells). "While our study provides strong evidence for the expression of RAG complex (RAG1/RAG2) in glioma cells and cleavage at cryptic RSS within fragile regions leading to chromosomal rearrangements, there are certain limitations." (PMID 41362770, 2025). "The role of RAG1 and RAG2 in glioma cells, as well as the precise mechanisms underlying the regulation of RAGs in glioma, is currently being investigated in detail in our laboratory." (PMID 41362770, 2025). "Significant expression of RAG1 was seen in all human glioma cell lines." (PMID 41362770, 2025). "Furthermore, mRNA levels are unchanged for the Th17-activating cytokine, IL-23, in normal, WT-glioma and Rag1−/−-glioma mouse brain (33±51%, −16.3±65% and 102±96%, respectively)." (PMID 21060663, 2010). "This coordinated expression of RAG1 and RAG2 indicates that they share a common regulatory mechanism and possible co-dependency in glioma cells." (PMID 41362770, 2025). "We were interested in determining if RAG1 and RAG2 interact with each other such as lymphoid cells and can form a complex within the glioma cells." (PMID 41362770, 2025). "In summary, using various molecular biology techniques, we show that RAG1 and RAG2 proteins are expressed in different glioma cell lines, although the overall expression level was lower than the pre-B cell lines." (PMID 41362770, 2025). "Firstly, we assessed the expression levels of RAG1 and RAG2 across a series of glioma cell lines, U251, U87, T98G, U118, and LN229." (PMID 41362770, 2025). "To investigate the expression pattern of RAG1 and RAG2 in patients with glioblastoma, we analyzed RNA-seq data of 693 patient samples obtained from the Chinese Glioma Genome Atlas (CGGA) database." (PMID 41362770, 2025). "We showed the coexpression and interaction of RAG1 and RAG2 in glioma cells; however, the upstream regulatory mechanisms leading to their reactivation in the non-lymphoid cells are yet to be elucidated." (PMID 41362770, 2025). "In conclusion, our findings provide compelling evidence for the role of RAG1 and RAG2 in the generation of chromosomal deletions and rearrangements within glioma cells." (PMID 41362770, 2025). "Our investigation provided compelling evidence affirming the expression of RAG1 and RAG2 in glioma cell lines, such as U251, U87, T98G, A172, U118, and LN229." (PMID 41362770, 2025). "Importantly, we also observed that RAG1 present in the glioma cells could interact with RAG2, and it could catalyze a significant level of pathogenic recombination between conventional 12RSS and 23RSS within the glioblastoma cells, which was dependent on the activity of RAGs present in the cells." (PMID 41362770, 2025). "Further immunofluorescence (IF) analysis was performed to evaluate the expression of RAG1 and RAG2 at the intracellular level in two glioma cell lines." (PMID 41362770, 2025). "Glioma cells deficient for galectin-1 showed reduced tumor growth, increased intra-tumor NK cell infiltration, and elevated expression of granzyme B when implanted into the striatum of Rag1−/− mice (which develop NK, but not T or B cells) when compared to Rag1−/− mice injected with wild-type cells." (PMID 32063906, 2020). "Here we investigate the role of 10 potential SNPs in XRCC3, BRCA2, RAG1, XRCC5, LIG4, XRCC4 and ATM in the development of gliomas, and further evaluate their gene-gene and gene-environment interactions in the development of glioma." (PMID 23663450, 2013). "Besides, RAG1 and RAG2 expression were lower in glioma cell lines compared to the Nalm6, a pre-B cell line." (PMID 41362770, 2025). "This suggests that both RAG1 and RAG2 are differentially expressed across glioma cell lines." (PMID 41362770, 2025).
glioma (continued). "Importantly, we established that both RAG1 and RAG2 are expressed in glioma cells, form a complex, and play a pivotal role in the generation of chromosomal deletions and rearrangements." (PMID 41362770, 2025). "Whereas human pediatric PA cells did not form gliomas in wild type mice, both Rag1−/− and Cxcl10−/− mice developed LGGs at 1mpi and 6mpi." (PMID 35986378, 2022). "We genotyped 10 potentially functional single nucleotide polymorphisms (SNPs) in 7 DNA double-strand break repair pathway genes (XRCC3, BRCA2, RAG1, XRCC5, LIG4, XRCC4 and ATM) in a case–control study including 384 glioma patients and 384 cancer-free controls in a Chinese Han population." (PMID 23663450, 2013). "However, IL-17A mRNA is detectable in glioma of WT mice, but not in glioma of Rag1−/− mice." (PMID 21060663, 2010). "Importantly, we could not detect mRNA for the Th17-secreted cytokine, IL-17A, in Rag1−/− mice with glioma, suggesting that T or B cells are required for IL-17A expression." (PMID 21060663, 2010). "However, no RAG1 or RAG2 was detected in the pull-down samples using the control DNA substrate lacking the 12RSS sequence, further confirming the specific binding of the RAG complex to the 12RSS substrate in the U87 glioma cell line." (PMID 41362770, 2025).
Granuloma (6 papers, 2015 to 2025). A compact, organized collection of mature mononuclear phagocytes, which may be but is not necessarily accompanied by accessory features such as necrosis. "Autoimmune cytopenia, granuloma, skin cancer, vasculitis, neuropathy, interstitial lung disease, and myopathy were detected in 76.2% of patients with RAG1, and 23.8% of the patients with RAG2 deficiency." (PMID 37724703, 2024). "The abundance and the architecture of granulomas per liver section was similar between WT and Rag1–/–at 3 dpi and of three Rag1–/– mice analyzed by H&E staining at 26 dpi, two had no granulomas and one had a single small resolving granuloma." (PMID 37865673, 2023).
Insulin resistance (6 papers, 2012 to 2022). Increased resistance towards insulin, that is, diminished effectiveness of insulin in reducing blood glucose levels. "Studies in Rag1−/− mice further confirmed the prominent role of CD8+ cells expressing STAT4 in insulin resistance and AT and islet inflammation." (PMID 28400678, 2017). "Furthermore, Rag1-/- mice developed insulin resistance, with impaired glucose and insulin tolerance, hyperinsulinemia and hyperglycemia within a week of feeding a diet with 60% kcal as fat." (PMID 35533183, 2022). "Another study revealed that after adoptive transfer into obese Rag1-null mice, CD4+ T cells gained a Th2 profile, indicated by the production of IL-4 and IL-13, which was associated with reversal of enhanced weight gain and insulin resistance in recipient obese Rag1-null mice." (PMID 30459770, 2018). "Following HFHSD, the Rag1-KO mice became obese, developed impaired glucose tolerance and insulin resistance, and showed non-compensatory stimulated insulin release despite being hyperinsulinemic." (PMID 33670429, 2021).